SYNPO2L (synaptopodin 2 like)
Description:
Actin-associated protein that may play a role in modulating actin-based shape.
Synonyms: FLJ12921; CHAP
Tractability: PROTAC: ubiquitination databases record sites on it.
Gene: Protein-coding gene on chromosome 10 (73,644,881 to 73,663,803, reverse strand). Ensembl gene ENSG00000166317.
Subcellular location: Cytoplasm, cytoskeleton
Gene Ontology:
Molecular function: protein binding; actin binding
Biological process: heart morphogenesis; positive regulation of actin filament bundle assembly; positive regulation of Rho protein signal transduction; positive regulation of stress fiber assembly; sarcomere organization
Cellular component: actin cytoskeleton; nucleus; Z disc; cytoskeleton; organelle
Genetic constraint (gnomAD): Loss-of-function variants: 35 observed, 47.97 expected, observed/expected ratio (o/e) 0.73, 90% interval 0.56 to 0.97. The upper end of that interval is the gene's LOEUF score, 0.97, which puts it in group 4 of 6, group 1 being the genes least tolerant of losing a copy. Missense variants: 1,246 observed, 1,242.2 expected, observed/expected ratio (o/e) 1, 90% interval 0.96 to 1.05. Synonymous variants: 536 observed, 507.74 expected, observed/expected ratio (o/e) 1.06, 90% interval 0.98 to 1.13.
Homologues: Orthologues: chimpanzee SYNPO2L (99% identical), macaque SYNPO2L (97% identical), dog SYNPO2L (91% identical), guinea pig SYNPO2L (89% identical), mouse Synpo2l (88% identical), rat Synpo2l (87% identical), pig SYNPO2L (85% identical), rabbit SYNPO2L (67% identical), tropical clawed frog synpo2l (48% identical), zebrafish synpo2lb (44% identical), zebrafish synpo2la (41% identical), Drosophila melanogaster CG1674 (13% identical). Paralogues in human: SYNPO2 (31% identical), SYNPO (15% identical).
Diseases named in the same sentence as SYNPO2L in open-access papers:
SYNPO2L is named in the same sentence as 22 diseases in open-access papers, as found by Europe PMC text mining. Sharing a sentence is not in itself a finding about the gene and the disease. The quoted sentences say what the papers report.
atrial fibrillation (10 papers, 2013 to 2025). A disorder characterized by an electrocardiographic finding of a supraventricular arrhythmia characterized by the replacement of consistent P waves by rapid oscillations or fibrillatory waves that vary in size, shape and timing and are accompanied by an irregular ventricular response. "Four SNPs near genes PITX2, ZFHX3, CAV1, and SYNPO2L are significantly linked with atrial fibrillation (AF), a significant stroke risk factor." (PMID 40863347, 2025). "A recent report indicates that loss-of-function variants in the SYNPO2L gene increase the risk of atrial fibrillation." (PMID 39195263, 2024). "The effect of SYNPO2L on actin and α-actinin activity demonstrated in this study might represent an essential physiological function of SYNPO2L, and help elucidate the pathogenesis of atrial fibrillation, especially those forms caused by SYNPO2L variants." (PMID 39195263, 2024). "Synpo2l encodes a cytoskeletal, heart-enriched, actin-associated protein; knock-down in zebrafish causes aberrant cardiac and skeletal muscle development and function, whereas human variants are associated with atrial fibrillation." (PMID 27604219, 2016). "What is more, a missense variant in SYNPO2L, rs3812629 (p.Pro707Leu) was found to confer risk to AF in the Framingham population by Whole Exome Sequencing in Atrial Fibrillation." (PMID 32902410, 2020). "SYNPO2L and PXN loci were associated with atrial fibrillation and flutter." (PMID 36598836, 2023).
cardiomyopathy (2 papers, 2023). A disease of the heart muscle or myocardium proper. "Genes associated with ER stress (e.g., ATF4, NUPR1, DDIT3, TRIB3, CHAC1, SESN2, HERPUD1) were upregulated and genes related to cardiomyopathy and sarcomeric structure (e.g., MYH7, SYNPO2L, LDB3, ACTN2, MYLK3) were downregulated by afatinib, sorafenib, or high-dose ponatinib." (PMID 37069550, 2023).
colorectal cancer (1 paper, 2024). A primary or metastatic malignant neoplasm that affects the colon or rectum. "Tissue samples from our colorectal cancer patient database also showed that high SYNPO2L expression patients have higher Mesenchymal CAFs Cell Marker levels than low expression patients." (PMID 39247832, 2024). "By constructing an overexpression lentivirus plasmid of SYNPO2L and introducing it into colorectal cancer cell lines in colony formation experiments, we observed that overexpression of SYNPO2L significantly promoted tumor cell growth." (PMID 39247832, 2024). "We first validated its impact on tumor cells by knocking down SYNPO2L in vitro in colorectal cancer cell lines." (PMID 39247832, 2024). "Continuing our analysis of the TCGA colorectal cancer patient transcriptome, we found that SYNPO2L can promote the expression of certain secretory proteins and is an important gene affecting protein secretion." (PMID 39247832, 2024).
dilated cardiomyopathy (1 paper, 2022). Cardiomyopathy which is characterized by dilation and contractile dysfunction of the left and right ventricles. "In addition to the known missense variant (rs2234962) in the BAG3 locus for dilated cardiomyopathy, we identify deleterious or damaging protein-coding variants in genes SYNPO2L, ERBB2, and STARD3 in strong LD with sentinel SNPs (LD R2 > 0.8)." (PMID 36517512, 2022).
lymph node metastasis (1 paper, 2024). "We observed that the distant metastasis, lymph node metastasis, invasion depth and ages of late stage patients, and the expression of SYNPO2L are significantly related to late stage cancer in patients." (PMID 39247832, 2024).
tumor (3 papers, 2024 to 2025). "Thus, we strongly suspect that SYNPO2L regulates tumor-associated fibroblast infiltration by controlling COL10A1, thereby playing its role." (PMID 39247832, 2024). "SYNPO2L promotes COL10A1 secretion and infiltration of tumour-associated fibroblasts, thereby promoting epithelial-mesenchymal transition (EMT) in tumour cells, making them more likely to develop distant metastases." (PMID 40463716, 2025). "Through colony formation experiments, we found that knocking down SYNPO2L significantly slowed down cell proliferation and migration, indicating its crucial role in tumor growth." (PMID 39247832, 2024). "Our prior research indicates that SYNPO2L is an important factor affecting tumor stages and poor patient prognosis." (PMID 39247832, 2024). "We found that SYNPO2L can affect the secretion of COL10A1 in tumor cells, thereby mediating the involvement of tumor-associated fibroblasts." (PMID 39247832, 2024). "SYNPO2L promotes the secretion of COL10A1 and the infiltration of tumor-associated fibroblasts, thereby facilitating Epithelial-Mesenchymal Transition (EMT) in tumor cells and making them more prone to distant metastasis." (PMID 39247832, 2024). "Similar results were observed in in vivo subcutaneous tumorigenesis experiments with nude mice, where overexpression of SYNPO2L effectively promoted tumor growth." (PMID 39247832, 2024). "Our studies also find that SYNPO2L has a significant role in affecting the chemotaxis of tumor fibroblasts." (PMID 39247832, 2024). "In fact, SYNPO2L plays an obvious role in promoting tumor growth." (PMID 39247832, 2024). "We found that knocking down SYNPO2L significantly affects tumor growth." (PMID 39247832, 2024). "To study SYNPO2L's role in tumor metastasis, we conducted cell migration assays." (PMID 39247832, 2024). "However, knocking down SYNPO2L significantly reduced tumor cell migration under co-cultured conditions, indicating the significant impact of SYNPO2L on tumor migration." (PMID 39247832, 2024). "Our previous research showed that SYNPO2L affects tumor growth." (PMID 39247832, 2024). "Furthermore, through in vivo subcutaneous tumorigenesis experiments in nude mice, we injected the SYNPO2L-knockdown cell line subcutaneously into nude mice and observed tumor growth in the mice." (PMID 39247832, 2024). "Interestingly, when METTL16 was knocked down while SYNPO2L was overexpressed, tumor growth and migration were similar to the control group." (PMID 39247832, 2024). "Our previous experiments showed that SYNPO2L, through COL10A1, interacts with CAFs to drive tumor progression and metastasis." (PMID 39247832, 2024). "Therefore, we conducted several experiments and found that SYNPO2L regulates the secretion of COL10A1 by tumor cells, thus guiding the occurrence of tumor metastasis." (PMID 39247832, 2024). "Both in vivo and in vitro experiments suggest that the absence of SYNPO2L inhibits tumor growth." (PMID 39247832, 2024).
cancer (1 paper, 2024). A tumor composed of atypical neoplastic, often pleomorphic cells that invade other tissues. "Subsequently, using Weighted Gene Co-expression Network Analysis (WGCNA), we discovered that SYNPO2L can regulate COL10A1, mediating the actions of Cancer-Associated Fibroblasts." (PMID 39247832, 2024).
SYNPO2L also shares sentences with these, for which no sentence is quoted: cardiovascular diseases (2 papers); Hypertension (2); Anxiety (1); Arrhythmia (1); colon cancer (1); coronary artery disease (1); COVID-19 (1); diabetes (1); gestational hypertension (1); heart diseases (1); heart failure (1); mental disorder (1); mild cognitive impairment (1); myofibrillar myopathy (1); Streptococcus pneumoniae infections (1).